HOTAIR (HOX transcript antisense RNA)
Diseases named in the same sentence as HOTAIR in open-access papers (continued):
Sharing a sentence is not in itself a finding about the gene and the disease.
tumor (continued). "Higher HOTAIR level has been proved to be associated with larger tumor size, advanced pathological stage, extensive metastasis and poorer survival." (PMID 26962687, 2016). "High expression of HOTAIR was associated with increased vascular invasion, advanced tumor stage, metastasis and poor prognosis." (PMID 27340923, 2016). "It has been shown that HOTAIR expressed highly in high-risk gastrointestinal stoma tumors, and the high expression levels were related to tumor metastasis." (PMID 27751178, 2016). "An important member of the class of tumor-associated lncRNAs is HOTAIR, which is overexpressed, by as much as 2000-fold in breast cancer patient tumors compared to normal tissue." (PMID 26800519, 2016). "Further in vivo studies demonstrated that the stable overexpression of miR-663b or knock-down of HOTAIR inhibited tumor growth and was associated with IGF2 expression." (PMID 27895308, 2016). "Above all, HOTAIR is associated with the tumor tumorigenesis and development of OS and can serve as a potential treatment target clinically in future." (PMID 27660759, 2016). "Overexpression of HOTAIR in tumor tissues was reported to be associated with increased risk of recurrence after hepatectomy, as well as positively correlate with lymph node metastasis." (PMID 25954300, 2015). "HOTAIR upregulation was associated with lymph node metastasis and large tumor size as well as inferior DFS after resection or transplantation, revealing its potential as marker of unfavorable patients' prognosis." (PMID 26064090, 2015). "HOTAIR expression is increased in pancreatic tumors compared with non-tumor tissue and is associated with more aggressive tumors." (PMID 26172293, 2015). "Depletion of HOTAIR by siRNA led to decreased invasion and increased apoptosis in HepG2 cells, and tumor growth was significantly inhibited in mice injected with HOTAIR-deficient cells." (PMID 25334066, 2014). "On one hand, they underlined the prognostic potential of HOTAIR expression level in tumor tissues of CRC patients, both in univariate analysis (p = 0.046) and multivariate analysis (p = 0.048)." (PMID 25334066, 2014). "Recent studies suggest that HOTAIR overexpression is positively associated with increased tumor cell malignancy." (PMID 24013378, 2013). "In addition, lncRNAs such as H19 and HOTAIR are closely associated with apoptosis, enhancing the resistance of tumor cells to apoptotic signals by regulating intracellular signaling pathways, and further promoting the immune escape of tumors." (PMID 40149989, 2025). "Furthermore, we observed associations between HOTAIR and miR-130a expression levels and several clinical characteristics of the disease, including tumor size, stage, and metastasis." (PMID 38114755, 2023). "Finally, we classified tumor types and found that high HOTAIR expression was associated with worse OS in STAD and ESCA." (PMID 36924407, 2023). "Thus, MALAT1, LUCAT1, and TUG1 are associated with the survival of patients with LC; HOTAIR can serve as a biomarker of tumour progression; and NEAT1 is related to poor prognosis." (PMID 38203731, 2023). "The expression of HOTAIR was associated with the size and stage of tumor." (PMID 35186192, 2022). "In addition to the HOTAIR level, the genetic polymorphism of HOTAIR can alter the development or progression of neoplasm." (PMID 36361470, 2022). "However, only the expression level of HOTAIR was significantly associated with the size and stage of the tumor (P < 0.05)." (PMID 35186192, 2022). "Studies have showed that upregulation of HOTAIR was linked to tumor malignant progression." (PMID 36438563, 2022). "Therefore, there is an urgent need to understand the biology and mechanism underlying the role of HOTAIR in tumor behavior and its potential as a biomarker for predicting the effect of chemotherapy." (PMID 36100611, 2022).
tumor (continued). "Moreover, numerous independent studies have unanimously reported HOTAIR was closely associated with tumorigenesis, tumor staging, metastasis, invasion, proliferation, and apoptosis in human solid cancers." (PMID 34367966, 2021). "Furthermore, high HOTAIR expression was closely associated with larger tumor size, extensive metastasis, and advanced pathological stages, and also correlated with shorter overall survival of GC patients." (PMID 34367966, 2021). "Loss-functional experiments revealed that HOTAIR knockdown could restrain the proliferation, migration and invasion of BC cells in vitro, and reduce the tumor growth of BC in vivo." (PMID 32694942, 2020). "Similarly, a clinical study revealed that high HOTAIR expression in primary breast tumors was significantly associated with worse prognosis, particularly in estrogen receptor (ER)-positive tumor samples." (PMID 32929060, 2020). "The performed meta-analysis showed that high expression of HOTAIR was significantly associated with venous invasion (OR = 2.53, 95% CI: 1.12-5.68, P = 0.02), advanced tumor infiltration (OR = 3.35, 95% CI: 1.34-8.42, P = 0.01) and distant metastasis (OR = 5.52, 95% CI: 1.22-25.01, P = 0.03)." (PMID 32104724, 2020). "HOTAIR was upregulated in EC tissues as compared to normal endometrial tissues and a higher level of HOTAIR expression was significantly associated with higher tumor grade, positive lymph node metastasis, the depth of myometrial invasion and the presence of lymphovascular space invasion." (PMID 30781521, 2019). "The evidence of HOTAIR induction in EMT and tumor progression and its causal role for epithelial gene repression (previously demonstrated in hepatocytes and, here, in colon cells) led us to investigate the transcriptional control of HOTAIR gene." (PMID 30154449, 2019). "In in vitro models, drug resistance induced by elevated HOTAIR expression may be caused by the promotion of tumor sphere cell growth and activation of tumor stem cell biomarkers such as Nanog, Oct3/4, Sox2, c-Myc, β-catenin, and Klf4." (PMID 31072041, 2019). "As we have known that HOTAIR might be associated with the effect of radiation on tumor, the impact of HOTAIR overexpression on cell viability and cell apoptosis was detected in cells exposed to radiation." (PMID 30355300, 2018). "Similarly, when we checked the clinical association of the lncRNAs screened in the present study in TANRIC database, lncRNAs H19, MEG3 and MALAT1 showed significant association with tumor stage and HOTAIR had a significant association with patient survival." (PMID 29719612, 2018). "Although there is a positive correlation between the expression of HOTAIR and tumor progression, the underlying mechanism of HOTAIR in tumorigenesis and development remains unclear." (PMID 28591050, 2017). "However, the association between HOTAIR expression and tumor progression and prognosis remains controversial." (PMID 28591050, 2017). "Here we identified HOTAIR and other tumor-associated lncRNA, in cell line exosomes and UEs from patients with HGMI (pT2-pT4) UBC, supporting the idea that UEs may contain lncRNA for biomarker discovery." (PMID 26800519, 2016). "Genetic variants of HOTAIR may affect the activity of certain regulatory factors and further regulate the aberrant expression of HOTAIR, which might be underlying mechanisms that affect tumour susceptibility and prognosis." (PMID 27010768, 2016). "Higher expression level of HOTAIR was associated with larger tumour." (PMID 27897239, 2016). "Increased HOTAIR expression was strongly associated with depth of tumor invasion, lymph node metastasis, organ metastasis, pathological differentiation, vascular invasion, and tumor progression." (PMID 27686732, 2016). "Knock-down of HOTAIR in Panc-1cells suppressed the in vivo tumor growth, suggesting that the in vivo tumor suppressive effect of miR-663b may be associated with HOTAIR." (PMID 27895308, 2016).
tumor (continued). "HOTAIR may be associated with the genome-wide reprogramming of PRC2 in a broad number of tumor types." (PMID 25275300, 2014). "However, a study of HCC patients showed that patients with HOTAIR overexpression exhibit larger tumor size, worse prognosis, and an increased risk of metastasis when compared to patients with normal HOTAIR levels." (PMID 25334066, 2014). "Therefore, we can hypothesize that HOTAIR expression and mutation are potential parts of tumor biology." (PMID 38696320, 2024). "Moreover, HOTAIR’s reach extends to the immunological realm of the tumor, potentially skewing the polarization of tumor-associated macrophages (TAMs) and implicating itself in the dual narratives of angiogenesis and immune evasion within the tumor." (PMID 39286016, 2024). "HOTAIR is linked to the formation of several tumors, and one of the mechanisms is that HOTAIR controls several downstream targets via different signaling pathways, which are linked to tumor cell motility, proliferation, angiogenesis, invasion, and drug resistance." (PMID 38270295, 2024). "In addition, HOTAIR may be a reasonable biomarker for predicting tumor risk, diagnosis, and metastasis." (PMID 34367966, 2021). "Furthermore, HOTAIR has been linked to drug resistance in several types of tumor." (PMID 34745939, 2021). "However, relatively greater HOTAIR expression (≥ 1.5) was significantly correlated with features also associated with tumour recurrence (e.g., tumour size (P = 0.030), lymphovascular space invasion (LVSI) (P = 0.037), and lymph node (LN) metastasis (P = 0.043))." (PMID 27323817, 2016). "HOTAIR (HOX transcript antisense RNA) contributes to MM pathogenesis through epigenetic repression of tumor suppressors and activation of NF-κB and JAK2/STAT3 signaling." (PMID 41596492, 2026). "Their interaction and positive feed-forward loop, perpetuated by JMJD6 and YBX1 inter-regulation, culminates in HOTAIR induction, which in turn is known to drive tumour progression." (PMID 40855961, 2025). "Antisense oligonucleotides targeting HOTAIR have shown promise in preclinical studies by inhibiting tumor growth and metastasis in luminal and TNBC subtypes." (PMID 41011238, 2025). "Our findings indicate that HOTAIR regulates the expression of various enzymes involved in glycolytic and glutaminolytic metabolism in tumor cells." (PMID 40072116, 2025). "HOTAIR, the first lncRNA confirmed to play a crucial role in tumor invasion and metastasis, also shows significantly higher expression in GC tissues compared to adjacent tissues." (PMID 39668941, 2025). "In this sense, we observed that HOTAIR is overexpressed in tumor tissue (9.31-fold, p ≤ 0.005) compared to healthy tissue and, in turn, increases according to the clinical stage." (PMID 40072116, 2025). "HOTAIR is also upregulated in PCa and promotes its proliferation, while its inhibition hinders tumor progression." (PMID 39825964, 2025). "The high expression of HOTAIR and EZH2 has been associated with tumor progression and poor prognosis." (PMID 41353219, 2025). "Stable and specific in biofluids, noncoding RNAs such as oncogenic miR‐21, tumor‐suppressive miR‐34a, and metastasis‐associated MALAT1/HOTAIR further enhance clinical applicability." (PMID 40959208, 2025). "HOTAIR promotes invasion, tumor growth, and metastasis through multiple pathways, including the PI3K/Akt/mTOR signaling pathway, which is crucial for cellular metabolism." (PMID 39858015, 2025). "Experimental data revealed that the overexpression of HOTAIR resulted in a twofold increase in the number of autophagosomes and a 50% improvement in cell survival, underscoring its pro-tumor function in the later stages of NSCLC." (PMID 40723840, 2025). "Collectively, these findings emphasize the multifaceted role of HOTAIR in epigenetic regulation, tumor metastasis, radioresistance, and stem cell maintenance in BC, rendering it a potential prognostic factor and a suitable therapeutic target." (PMID 40141248, 2025).
tumor (continued). "miR-31 and other tumor-suppressive microRNAs are downregulated through promoter hypermethylation, while oncogenic lncRNAs like HOTAIR and ANRIL are upregulated, contributing to immune evasion and proliferative advantage." (PMID 40557320, 2025). "lncRNAs have emerged as critical regulators in CC progression, as exemplified by well‐characterized oncogenic and tumor‐suppressive lncRNAs such as HOTAIR and PVT1." (PMID 40665897, 2025). "Based on our findings, we recommend investigating targeted HOTAIR inhibitors in clinical practice to reduce tumor resistance and combining them with PD‐L1 inhibitors to further enhance immune efficacy." (PMID 40235720, 2025). "HOTAIR, the first identified trans-acting lncRNA, has been observed to exhibit abnormally high expression levels in various tumor tissues and cell lines." (PMID 40534842, 2025). "Numerous studies have highlighted HOTAIR’s role and its interaction with histone modification complexes, contributing to the epigenetic silencing of tumor suppressor genes." (PMID 40149464, 2025). "We found that the expression of 9 DE-ceRNAs were significantly different between tumor tissues and normal tissues, including the upregulated H19, HOTAIR, miR222, miR148a, PCDHGB4, GMNC and HMGA2 and the downregulated LRP2 and MBP in tumors." (PMID 40351420, 2025). "Recent studies revealed that HOTAIR overexpression plays a crucial role in tumour initiation and progression, and is an important modulator of chemoresistance." (PMID 38887279, 2024). "The results of COX regression analysis indicated that the levels of HOTAIR in tumor tissue and peripheral blood were independent predictive factors of OS and PFS in patients with advanced HCC who were treated with Sunitinib." (PMID 39596302, 2024). "For example, the suppression of specific lncRNAs like MALAT1 and HOTAIR has shown to inhibit tumor growth and metastasis in animal models." (PMID 39512820, 2024). "The application of irradiation also suppressed the tumorigenesis of CRC cells in nude mice, and HOTAIR silencing synergized with irradiation treatment to suppress the tumor formation." (PMID 39055884, 2024). "HOTAIR expression was also found in lymphocytes inside the tumor, and the expression decreased in lymphocytes further from the tumor." (PMID 38601651, 2024). "Further, inhibition of HOTAIR and the consequent removal of miR-326 silencing were found to protect nude mice challenged with orthotopic tumor transplantation." (PMID 38366205, 2024). "HOTAIR knockdown inhibited tumour growth in a xenograft mode, whereas killing of miR-129-5p reversed the silencing function of HOTAIR and FZD7 restored the suppressive function of miR-129-5p, suggesting that HOTAIR controls the miR-129-5p/FZD7 axis." (PMID 38528461, 2024). "Further investigation showed that down-regulated HOTAIR in stem cells suppressed the tumor growth and lung metastasis in the nude mouse model." (PMID 38725621, 2024). "The involvement of HOTAIR in immunotherapy should be further validated through clinical and cellular experiments, such as co-culturing tumor cells with immune cells using interference for HOTAIR." (PMID 38696320, 2024). "Further studies with a larger sample size will help to draw reliable conclusions about the expression of HOTAIR in tumor tissues." (PMID 38696320, 2024). "From a prognostic perspective, patients with low levels of HOTAIR in tumor tissues displayed significantly prolonged survival (13.4 vs. 9.5 months) and PFS (8.4 vs. 6.2 months) compared to those with high expression levels." (PMID 39596302, 2024). "For example, the lncRNA MALAT1 induces tumor cell proliferation and metastasis by regulating downstream genes in LUAD, and the lncRNA HOTAIR induces tumor cell proliferation and invasion by regulating downstream genes in LUAD." (PMID 38355480, 2024).
tumor (continued). "HOTAIR (HOX transcript antisense intergenic RNA): In HCC, HOTAIR has been identified as an oncogene playing a crucial role in promoting tumor growth and HCC development while suppressing apoptosis." (PMID 39448589, 2024). "We found a positive correlation between the age, gender, race and tumor stage and expression level of HOTAIR at the same time in ACC, BRCA, COAD, KIRC, MESO and THYM." (PMID 38696320, 2024). "HOTAIR has been found to be upregulated in NSCLC and is associated with tumor invasion and metastasis." (PMID 39452836, 2024). "The relative expression levels of HOTAIR were examined in 70 pairs of CRC tumor and para-cancerous tissues, as well as in radiosensitive and radioresistant samples." (PMID 39055884, 2024). "Further examination of HOTAIR expression in CC cell lines showed consistent results, with HOTAIR notably overexpressed in the HeLa cell line compared to non-tumor cell lines." (PMID 39273054, 2024). "A recent study demonstrated that the expression of lncRNA HOTAIR was significantly increased in the OC patient’s tumor tissues and OC stem cells compared with controls." (PMID 38725621, 2024). "For example, HOTAIR, one of the earliest reported lncRNAs, has been recognized as a significant oncogenic driver, contributing to tumor cellular signaling transduction, cancer metabolism reprogramming, and tumor metastasis." (PMID 38555465, 2024). "Several recent genome-wide analysis (GWAS), microarray, and ddPCR studies show that aberrant HOTAIR expression is associated with the clinicopathological features of PTC, such as lymph node metastasis, tumor stage, and response to therapy." (PMID 38339237, 2024). "Increased transcription of HOTAIR in various cancerous tissues is accompanied by shorter overall survival and disease-free survival, metastasis, and tumor resistance to chemo/radiotherapy." (PMID 38157198, 2024). "For example, the lncRNA MALAT1 and HOTAIR were overexpressed in ESCC tumor tissues and served as good predictive factors for overall survival." (PMID 38457049, 2024). "Given the important role of HOTAIR in a variety of tumors, we further explored the correlation between tumor immunity and HOTAIR." (PMID 38696320, 2024). "Tumor-derived HOTAIR directs B cells towards a regulatory phenotype characterized by programmed cell death-ligand 1 (PDL1) expression in CRC, thereby inducing PDL1-expressing B cells to suppress CD8+T cell activity." (PMID 38696320, 2024). "After 4 weeks, the analysis of xenograft tumor samples showed that HOTAIR silencing attenuated tumor growth in vivo." (PMID 39055884, 2024). "High HOTAIR expression promotes the recruitment of macrophages and myeloid suppressor cells into the tumor microenvironment through the secretion of cytokines and/or chemokines by hepatocellular tumor cells." (PMID 38339237, 2024). "We observed a significant correlation between HOTAIR expression and tumor immune cell infiltration, including B cells, CD8+ T cells, CD4+ T cells, macrophages, neutrophils, and dendritic cells." (PMID 38696320, 2024). "Serum HOTAIR levels were closely associated with the HCC stage, metastasis, vascular invasion, and tumor size." (PMID 39596302, 2024). "The authors demonstrated that the expression of HOTAIR was significantly higher in tumor tissues than in adjacent non-tumor tissues." (PMID 39596302, 2024). "HOTAIR’s influence on angiogenesis is multifaceted; it is postulated to reshape the tumor microenvironment by orchestrating the delicate balance of cytokines and growth factors, including VEGF and FGF." (PMID 39286016, 2024). "Xie and colleagues conducted a study examining the levels of HOTAIR in exosomes originating from colorectal cancer cells and in B cells that infiltrate the tumor." (PMID 38887279, 2024). "For example, the lncRNA HOTAIR has been proposed as a potential therapeutic target for the treatment of breast cancer, as its inhibition has been shown to reduce tumor growth and metastasis in preclinical models." (PMID 39257589, 2024).